UMOD (uromodulin)
Diseases named in the same sentence as UMOD in open-access papers (continued):
Sharing a sentence is not in itself a finding about the gene and the disease.
kidney disease (continued). "The enzyme-linked immunosorbent assay (ELISA) for the IgA–uromodulin complex was developed and applied to urine samples obtained from various kidney disease patients." (PMID 22415778, 2012). "Background and Clinical Significance: Autosomal dominant tubulointerstitial kidney disease caused by a mutation in the uromodulin gene (ADTKD-UMOD) is a rare kidney disorder characterized by progressive tubulointerstitial damage and a slowly progressive loss of renal function." (PMID 42196832, 2026). "Low serum uromodulin levels may be correlated with kidney function and renal disease activity in lupus nephritis and ANCA-associated glomerulonephritis." (PMID 40564142, 2025). "However, beyond ADTKD-UMOD, the association between uromodulin and kidney diseases has largely been correlative, underscoring the need for direct mechanistic insights to enable development of effective, rational therapies." (PMID 40519162, 2025). "In this original research article, we elucidate the pivotal role that Transmembrane Emp24 Protein Transport Domain Containing (TMED) cargo-receptors—specifically, TMED2, TMED9, and TMED10—play in the pathogenesis of a kidney disease associated with uromodulin (UMOD)." (PMID 39680459, 2024). "It is essential to recognize the possibility that UMOD single nucleotide polymorphisms (SNPs) may have additional effects unrelated to uromodulin production, which might be involved in the association with kidney disease." (PMID 37835820, 2023). "This serum uromodulin level is closely associated with kidney function and histological severity, suggesting its potential as a biomarker capable of reflecting disease severity across a spectrum of kidney disorders." (PMID 37835820, 2023). "Integrating genetic data with uromodulin biomarker levels could enable the identification of individuals at high risk of kidney diseases or those who may respond better to certain treatments." (PMID 37835820, 2023). "In clinical studies, both circulating and urinary uromodulin levels have been shown to be protective against kidney disease as well as cardiac and all-cause mortality, suggesting that elevated levels of uromodulin could be advantageous." (PMID 35163625, 2022). "Defective uromodulin processing is associated with various kidney disorders." (PMID 31444371, 2019). "Based on these observations, we speculated that powerful genes such as UMOD causing the Mendelian form of kidney diseases might be involved in more common mechanisms of CKD progression as modifier genes." (PMID 30868372, 2019). "In summary, we report a novel UMOD mutation in a Brazilian family with 11 affected members, and we discuss the importance of performing genetic testing in families with inherited kidney disease of unknown cause." (PMID 29513881, 2018). "Seven of the ten distinct gene mutations were published mutations and listed in the Wake Forest Inherited Kidney Disease Database for uromodulin associated kidney disease (variant p.(Thr62Pro) was listed as clinically silent), and three of these were also present in the Human Gene Mutation Database." (PMID 30376835, 2018). "In our pilot study, we found that a panel of seven biomarkers (dodecanal, 8-hydroxyguanosine, leukotriene C4, α1-antitrypsin, IgA-uromodulin complex, galactose-deficient IgA1, and heparan sulfate) differentiated patients with IgAN from patients with other kidney diseases and healthy controls." (PMID 27799660, 2016). "In summary, we found that urinary uromodulin levels are associated with interstitial fibrosis/ tubular atrophy and contribute to eGFR decline in IgAN, implicating a protective role of uromodulin in kidney disease progression." (PMID 23990922, 2013). "Uromodulin may be only a marker of tubular damage, or it could also be a factor involved in the pathogenic process of renal disease." (PMID 23990922, 2013).
kidney disease (continued). "However, we did find that both time average proteinuria and uromodulin were associated with eGFR decline, which is a commonly used endpoint in kidney disease." (PMID 23990922, 2013). "For example, pathogenic mutations in genes such as APOL1 and UMOD, which are associated with the onset of CKD, occur at varying frequencies across different ethnic groups, contributing to the disparities in kidney disease risk." (PMID 40069100, 2025). "In these kidney diseases, impaired uromodulin export dynamics lead to an intracellular accumulation of this protein in the tubular epithelium of the thick ascending limb of Henle’s loop." (PMID 40564142, 2025). "In 2017, his group published a review: Uromodulin: from physiology to rare and complex kidney disorders, which was co-cited up to 155 times and had the citation bursts from 2017 to 2022." (PMID 37322316, 2024). "Creatinine is an accurate marker of kidney disease and, for this reason, we expected a significant relationship between uromodulin and creatinine." (PMID 39061561, 2024). "Biological annotation found evidence for three novel decline-associated loci to capture common-variant-effects for genes of rare Mendelian kidney diseases (SDCCAG8, RRAGD, and MUC1), additional to the two such genes in known eGFR-decline loci (UMOD, PRKAG2)." (PMID 39567532, 2024). "Urinary uromodulin excretion serves as a surrogate for tubular mass and function in the general population and in patients with renal diseases." (PMID 38236469, 2024). "From our results, we conclude that urinary uromodulin is more related to kidney disease than serum uromodulin." (PMID 39061561, 2024). "In recent years, a positive correlation between serum uromodulin levels and kidney function was confirmed by several studies on populations with kidney disease of different etiology." (PMID 37322316, 2024). "In stage 1 of CKD, urinary uromodulin correlated with kidney disease markers SDMA (p = 0.0424, p = 0.0214) and UPC (p = 0.0050, p = 0.0024)." (PMID 39061561, 2024). "We further investigated the correlation of uromodulin with common serum markers of kidney disease such as creatinine, urea, and SDMA." (PMID 39061561, 2024). "The UMOD protein, due to its apical and basolateral bidirectional secretion, plays a role in several biological processes in cardiovascular and kidney diseases." (PMID 39259220, 2024). "In the present review, we will give an overview of the general characteristics of uromodulin and its role in a wide spectrum of kidney diseases." (PMID 37835820, 2023). "The diverse functions of uromodulin and its interactions within the kidney highlight the complexity of kidney disease pathology." (PMID 37835820, 2023). "In various forms of kidney disease, interstitial uromodulin is closely correlated with serum uromodulin concentrations, although there is a concentration gradient between the medulla and cortex of the kidney." (PMID 37835820, 2023). "Higher serum uromodulin concentrations showed an inverse correlation with progression to advanced kidney disease in elderly participants in the population-based KORA study." (PMID 37835820, 2023). "Several studies have found uromodulin to be an important biomarker for kidney tubular damage and to predict progressive kidney disease in addition to the established biomarkers." (PMID 38139542, 2023). "We investigated the association between serum uromodulin levels and the main renal disease activity indices in SLE patients, such as the renal SLEDAI or SLICC renal disease activity scores." (PMID 36301848, 2022). "Here, we review the paradigm of UMOD, the gene coding for uromodulin, to illustrate how a kidney-specific protein of major physiological importance is involved in a spectrum of kidney disorders." (PMID 35881244, 2022).
kidney disease (continued). "Since, Umod is a major protein synthetized and secreted by the renal medulla, and since medullary hypoxic injury is crucial in kidney diseases, it was expected that serum uromodulin decreases in patients with chronic tubulointerstitial damage such as ON." (PMID 36556931, 2022). "First proposed in the 2015 Kidney Disease: Improving Global Outcomes (KDIGO) consensus report, ADTKD is currently believed to be caused by gene mutations UMOD, REN, MUC1, HNF1B, SEC61A, and DNAJB11." (PMID 36362756, 2022). "Uromodulin and cauxin are known markers of tubular damage and their decrease was already demonstrated in cats affected by kidney disease." (PMID 32397661, 2020). "For investigation of uromodulin, the study included also 15 patients with non-kidney diseases, all Caucasian, 7 men and 8 women." (PMID 32764335, 2020). "In this study, we have demonstrated that urinary uromodulin is a marker of kidney disease, with lower levels in CKD cases compared to those with normal kidney function." (PMID 31065383, 2019). "Urinary uromodulin levels are reduced in patients with kidney disease, due to a reduction in secretion from damaged tubules." (PMID 31065383, 2019). "Several genes, including UMOD, SHROOM3 and ELMO1 have been strongly associated with renal diseases, and some of their traits, such as eGFR and creatinine." (PMID 30359254, 2018). "Several genes, including UMOD, SHROOM3 and ELMO1 have been strongly associated with renal diseases, and some of their traits, such as eGFR and serum creatinine." (PMID 30359254, 2018). "One hundred and three of 126 urine samples (81.7%) from IgAN patients were positive for the IgA–uromodulin complex, while only 25 out of 94 urine samples (26.6%) in other kidney disease patients were positive." (PMID 22415778, 2012). "The role of uromodulin in the onset and progression of kidney disease is currently of great interest in clinical nephrology." (PMID 21235779, 2011). "In view of those data, uromodulin could be seen as a surrogate marker of nephron functional mass in heath as well as kidney disease." (PMID 38500759, 2024). "While much attention has been paid to its expression as a biomarker for kidney disease, recent years have witnessed a growing body of evidence linking uromodulin to cardiovascular events and mortality through numerous clinical and Mendelian randomization studies." (PMID 39049957, 2024). "Serum and urinary uromodulin are evaluated as potential biomarkers of kidney disease." (PMID 39061561, 2024). "However, in recent years, serum as well as urinary uromodulin have been investigated in relation to kidney diseases." (PMID 39061561, 2024). "The development of a uromodulin biosensor could have potential application value in clinical diagnostics, the monitoring of kidney function and the study of renal diseases." (PMID 38139542, 2023). "UMOD is hence a main driver of genetic kidney disease, and genetic studies of the kidney-specific protein uromodulin may yield insights not only into kidney disease but also into the protein’s other diverse functions and associated diseases." (PMID 35446786, 2022). "Uromodulin (UMOD) is a major risk gene for monogenic and complex forms of kidney disease." (PMID 35446786, 2022). "Loss of NM2 proteins from renal epithelial segments resulted in rapidly progressing kidney disease and revealed critical roles for NM2 proteins in regulation of unique, thick ascending limb–associated (TAL-associated) proteins uromodulin (UMOD) and Na+ K+ 2Cl– cotransporter (NKCC2)." (PMID 33001861, 2020). "Uromodulin is a protein which is produced by the tubular cells of the thick ascending limb in the kidneys and the creatinine to uromodulin ratio in serum recently has attracted interest as a marker of kidney disease." (PMID 28861439, 2017).
kidney disease (continued). "Biomarkers of type 0 that reflect tubular damage and have been under investigation in various settings of kidney disease are Neutrophil Gelatinase Associated Lipocalin (NGAL), Kidney Injury Molecule-1 (KIM-1), Uromodulin (UMOD), Clara Cell Protein 16 (CC16) and albuminuria." (PMID 25875363, 2015). "Although the physiological role of this protein remains unclear, recent studies have proposed low levels of UMOD as a biomarker of renal disease." (PMID 24498182, 2014). "Six of these proteins (uromodulin, α-1-microglobulin, zinc-α-2-glycoprotein, cystatin C, Ig-kappa-chain, and inter-α-trypsin heavy chain H4) were strongly correlated with various forms of kidney disorders." (PMID 21997203, 2012). "Whether or not the findings from FHS, a community-based study, extend across other settings is an important question to understand the potential of uromodulin protein as a biomarker for kidney disease onset and progression." (PMID 21235779, 2011). "In renal disease patients, uromodulin excretion was reduced in proportion to the extent of renal damage, and was a marker of distal tubular sodium reabsorption, but in these studies, the effects of BP on uromodulin were inconsistent." (PMID 21082022, 2010). "Furthermore, we observed a consistent and significant change in the abundance of several peptides that have been previously associated with the progression of kidney diseases, including alpha-1-antitrypsin, antithrombin-III (ATIII), CD99 antigen and uromodulin." (PMID 37930730, 2024). "However, the renal disease may influence this relationship, as severe renal impairment may attenuate the protective effects of uromodulin on calcification and lipid metabolism." (PMID 39049957, 2024). "Moreover, the decline in estrogen production and uromodulin with age in female patients may have a direct/indirect effect on the increased incidence of kidney disease in female patients with age that is normally observed in the clinical literature." (PMID 37768810, 2023). "Urinary uromodulin is an independent clinical factor associated with the progression of IgAN, and it potentially plays a dual role in CKD: damage to renal tubules may lead to reduced uromodulin synthesis, while uromodulin itself may also be involved in the pathogenesis of kidney disease progression." (PMID 37835820, 2023). "In the multivariable analysis after adjusting serum uromodulin by the eGFR, the risk of renal flare by the rSLEDAI was 2.94, independent of other variables, whereas the risk increased to 4.27 when a patient with flare had a SLICC renal disease activity score of ≥5." (PMID 36301848, 2022). "In a human pathologic study from patients with UMOD gene mutation, who had familial juvenile hyperuricemic nephropathy, ER stress marker GRP78 was found to be highly expressed in renal tubular compartment, indicating a possible association between ER stress and UMOD related kidney disease." (PMID 29340054, 2017). "A study that evaluated many markers, including uromodulin, for the diagnosis of the preclinical stage of CKD in children did not confirm uromodulin as a useful tool for the diagnosis of early stages of kidney disease." (PMID 39061561, 2024). "The trafficking dynamics of uromodulin (UMOD), the most abundant protein in human urine, play a critical role in the pathogenesis of kidney disease." (PMID 39680459, 2024). "This highlights the potential of using uromodulin and β2-microglobulin together as a more effective and sensitive indicator for evaluating disease progression and severity in SLE-related kidney disorders." (PMID 37835820, 2023). "Our results indicated that IgAN can be discriminated from other proteinuric kidney diseases such as DMN, MN, FGS and MCNS by the value of the urinary IgA–uromodulin complex." (PMID 22415778, 2012). "Since uromodulin (UMOD) has the smallest P value and a known role in eGFR and kidney disease, the UMOD could effectively serve as a positive control for our signal-identifying approach." (PMID 38898508, 2024).
kidney disease (continued). "Serum uromodulin levels also showed a negative correlation with the SLICC renal disease activity score (Rho = -0.29, p = 0.002)." (PMID 36301848, 2022). "Thus, the manifestation of a kidney disease pattern in patients carrying the Sec61α–V67G or Sec61α–T185A mutation could very well be explained by the substrate-specific retention of REN and eventually UMOD in or at the ER, thereby hampering their efficient secretion." (PMID 35064074, 2022). "Our research confirmed previous reports showing significantly higher s-Uromodulin in healthy controls (patients without kidney disease) compared to KTRs, who in general belong to the group of CKD patients." (PMID 32764335, 2020). "The lower levels of urinary uromodulin in CKD are postulated to be secondary to a reduction in the number of functional distal tubular cells and have been observed in previous case control studies on kidney disease." (PMID 31065383, 2019). "The healthy controls and the kidney disease patients had similar concentrations of uromodulin in urine (data not shown)." (PMID 22415778, 2012). "Because the IgA–uromodulin complex is found in the urine of almost all kidney diseases by ELISA, it does not seem to be specific to IgAN." (PMID 22415778, 2012). "Over time, Umod KO mice develop kidney calcification and may no longer demonstrate uromodulin function, but the consequences of kidney disease." (PMID 38211973, 2024). "Urinary uromodulin is not merely a reflection of the total functioning mass of Henle’s loop but rather a target of inducible regulation and an active participant in the intricate processes of kidney disease pathogenesis." (PMID 37835820, 2023).
cardiovascular disease (14 papers, 2013 to 2024). "Over the years, studies have revealed compelling associations between urinary and serum concentrations of uromodulin and various parameters, encompassing kidney function, graft survival, cardiovascular disease, glucose metabolism, and overall mortality." (PMID 37835820, 2023). "Reduced levels of urinary uromodulin have been associated with acute tubular necrosis, diabetic nephropathy, active lupus nephritis, mortality and cardiovascular disease." (PMID 33768217, 2021). "First, the cohort has a relatively short duration of follow-up and a limited number of cardiovascular events and death, which limited our power to investigate the association between the levels of uromodulin and cardiovascular disease." (PMID 30454063, 2018). "Research has shown that increased uromodulin expression may be associated with lower risk of cardiovascular disease in adults." (PMID 33768217, 2021). "Continued exploration of uromodulin's involvement in cardiovascular diseases holds potential benefits for this patient population, given the high prevalence of cardiovascular complications in CKD." (PMID 39049957, 2024). "This area presents an exciting avenue for future research into uromodulin's role in cardiovascular disease." (PMID 39049957, 2024). "The precise relationship between uromodulin and cardiovascular disease is subject to the ongoing investigation and may be influenced by factors such as ethnicity, age, and gender." (PMID 39049957, 2024). "While significant strides have been made in understanding uromodulin's role in cardiovascular disease, numerous unknown aspects warrant further exploration." (PMID 39049957, 2024). "Furthermore, the association of uromodulin, exclusively produced in the kidney, and the UMOD gene, exclusively expressed in the kidney, with cardiovascular disease, opens avenues for investigating cardiorenal syndrome and elucidating the intricate link between heart and kidney health." (PMID 39049957, 2024). "The recently published C-STRIDE study in CKD stage 1–4 patients (n = 2731, 40% women) of Chinese ethnicity, found that rs4293393 genotypes were associated with the risk of all-cause mortality but not the level of serum uromodulin, slope of eGFR decline or risk of cardiovascular disease events." (PMID 36443444, 2023).